EGFR (epidermal growth factor receptor)
Diseases named in the same sentence as EGFR in open-access papers (continued):
Sharing a sentence is not in itself a finding about the gene and the disease.
tumor (continued). "Despite comparable EGFR copy number alterations and EGFR expression levels, HCI-010 tumors treated with navitoclax+ABBV-321 achieved near-complete tumor regressions and pathological responses." (PMID 33256808, 2020). "TEX also demonstrated a higher affinity to EGFR resulting in activation of Akt/protein kinase B pathway and overexpression of VEGF and finally augmented tumour vascularity." (PMID 32570802, 2020). "The effects of EGFR/Ras on the expression and translation of CCL20 were analysed in a large set of epithelial cancer cell lines and tumour tissues by RT-qPCR and ELISA in vitro." (PMID 32601464, 2020). "Another emerging key player involved in osimertinib intrinsic resistance is the RTK Anexelekto (AXL), which can interact with other RTKs, including EGFR and HER3, and sustain survival of tumor cells exposed to osimertinib." (PMID 33392095, 2020). "The overexpression of EGFR or ERBB2 can promote the proliferation, migration, invasion, and angiogenesis of tumor cells, while suppress their apoptosis." (PMID 33287876, 2020). "Our data not only showed that RANK promoted tumor cell invasion through RANKL, but also suggested that there was crosstalk between the RANK/RANKL pathway and the EGFR signaling pathway." (PMID 31933009, 2020). "In addition, we assessed other factors that might contribute to drug accumulation and treatment efficacy, such as intra-patient variability in PK, tumor EGFR expression, plasma soluble EGFR (sEGFR) concentration, tumor perfusion on [15O]H2O PET/CT, and metabolic tumor activity on [18F]FDG PET/CT." (PMID 31705176, 2020). "The top 10 downregulated genes are involved in different signalling pathways, such as the CHN2 gene in the regulation of RAC1 activity, the FOS gene in EGFR signalling and ITGA7 in integrin pathways and Akt signalling and in tumour initiation and progression." (PMID 32613561, 2020). "Our results suggest that long-term treatment with genistein strikingly reduced EGFR expression, and genistein contributed to the reduced reactivity of EsC cells to EGF, which amplified the anti-tumor effect of genistein in EsC cells." (PMID 32276266, 2020). "This autocrine loop is amplified by tumor plasma cells that stimulate expression of HB-EGF and EGFR in MMEC." (PMID 31936715, 2020). "The high expression of NTN1, NTN3, and NTNG1 is also sensitive to MS-275 (HDAC inhibitor), RG-108 (DNA methyltransferase inhibitor), and CUDC-101 (HDAC inhibitor, EGFR inhibitor, and HER2 inhibitor), which inhibit tumor by affecting epigenesis." (PMID 32251318, 2020). "The dramatically increased BTC‐mediated tumor burden was EGFR‐dependent, but also ERBB4 and ERBB2 were involved in PDAC development or progression, as depletion of EGFR, ERBB2, or ERBB4 significantly improved the survival rate of BTC‐mediated PDAC." (PMID 32335999, 2020). "On the other hand, there are several reports on the relationship between tumor PD-L1 expression and the PFS after EGFR-TKI treatment." (PMID 33255696, 2020). "In patients with EGFR+/ALK+ and ≥25% tumor cells expression of PD-L1, the ORR and median OS were 12.2% and 13.3 months, which were significantly better lpagthan chemotherapy." (PMID 33392095, 2020). "Since immunotherapy can be proposed alone or in combination with first-line chemotherapy in patients whose tumors are wild type for EGFR, ALK, ROS1, and BRAF, it is obligatory to obtain the PD-L1 status of tumor cells." (PMID 32294880, 2020). "Cannabinoids reduce tumor proliferation by inhibiting the activation of the AKT, EGFR, ERK, and nuclear factor kappa beta (NF-κβ) signaling pathways." (PMID 33066359, 2020). "Meanwhile, Ki-67 staining in tumor tissue was decreased after ASK120067 treatment, confirming the antiproliferative activity of ASK120067 in the EGFR L858R/T790M PDX model." (PMID 32404161, 2020).
tumor (continued). "ASGR has been suggested to promote cancer metastasis by activating the EGFR–ERK pathway through interactions with counter-receptors on cancer cells, responding to endogenous lectins in the tumor microenvironment." (PMID 32983988, 2020). "Next, both xenograft tumor tissues were profiled by IHZ assay with Pb-S01 and Pb-S02 Probody reagents directed against EGFR." (PMID 32246002, 2020). "In contrast, epidermal growth factor receptor (EGFR) and AKT transcription increased, which explains the exacerbated proliferation of these tumor cells." (PMID 32168915, 2020). "Oral administration of ASK120067 induced tumor regression in NSCLC xenograft models and in a PDX model harboring EGFR T790M." (PMID 32404161, 2020). "In line with our findings in the tumor cell lines, the distribution and intensity of 14-3-3ζ were positively correlated with ID1 in human EGFR-mutant LUAD specimens (right)." (PMID 33123465, 2020). "Overall, this study demonstrated that Formo acts as an inhibitor for the EGFR-Akt axis, and promotes FBW7-mediated Mcl-1 ubiquitination is required for the anti-tumor activity of Formo both in vitro and in vivo." (PMID 32276600, 2020). "A recent report demonstrated that EGFR signaling influences proteasome activity by modulating the expression of the immunoproteasome subunits LMP7 and LMP2 in tumor plasma cells." (PMID 31936715, 2020). "Patients diagnosed with EGFR-mutant NSCLC have good initial clinical response to EGFR tyrosine kinase inhibitors (EGFR TKIs), yet tumor recurrence is common and quick to develop." (PMID 32292420, 2020). "For example, epidermal growth factor receptor (EGFR) is overexpressed by many different cancers and signaling via EGFR leads to tumor cell proliferation, migration, and invasion." (PMID 32698317, 2020). "The presence of EGFR in the E10 and BxPC3 derived EVs may suggest that the same mechanism is at play with the exchange of growth factor receptors between the cells of the primary tumors, as well as between the tumor cells and other cells in the tumor microenvironment and even cells in distant sites." (PMID 32886718, 2020). "When injected in high EGFR-expressing tumor-bearing mice, [18F]AlF-NOTA-PODS-ZEGFR:03115 and [18F]AlF-NODAGA-PODS-ZEGFR:03115 showed similar pharmacokinetics and a specific tumor uptake of 14.1 ± 5.3% and 16.7 ± 4.5% ID/g at 1 h post-injection, respectively." (PMID 32235296, 2020). "AT1R blockers (ARBs) have beneficial effects on tumor growth, vascularization, and metastasis by inhibiting AT1R-mediated transactivation of EGFR and induction of VEGF." (PMID 32708604, 2020). "HIF-1α has been shown to lie downstream of EGFR and AKT signaling and to activate VEGF expression in tumor cells." (PMID 32045997, 2020). "Oral administration of ASK120067 leads to tumor regression in cell-based and patient-derived xenograft (PDX) models harboring EGFR mutants." (PMID 32404161, 2020). "CRIS-C encompasses CIN tumours with wildtype KRAS status, MYC amplification and increased EGFR pathway activity." (PMID 32647253, 2020). "To compare EGFR, BCL-2, and BCL-XL expression levels within these tumor models, we performed IHC assays and H-score (H) assessment for each protein." (PMID 33256808, 2020). "In accordance with the suppression of tumor growth, KYA1797K significantly decreased β-catenin, pan-RAS, and EGFR levels as well as ERK and Akt activities, downstream of RAS." (PMID 32457491, 2020). "Epidermal growth factor receptor (EGFR) is often overexpressed in various tumor cells, leading to uncontrolled growth of tumor, and is regarded as an important target for developing novel antitumor drugs." (PMID 32411653, 2020).
tumor (continued). "Inhibiting PD-L1 allowed for further functioning of T cells via anti-EGFR-hmLIGHT within the Ag104Ld and MC38 tumor models, inducing complete rejection of established tumors in a therapeutic setting." (PMID 32499782, 2020). "After the transfer of mononuclear cells to tumor-bearing mice with EGFR-expressing tumor, administration of ICOVIR-15K into the tumor resulted in persistent accumulation of cytotoxic T cell (CTL) and increased antitumor effects." (PMID 32992948, 2020). "Recently, some studies reported that Afatinib had limited anti-tumor activity in CRPC patients, probably due to EGFR-targeted therapies desistance." (PMID 33224867, 2020). "Tumor samples in the present study had been stained for markers including NUT, P63, P40, TTF-1, keratin, CK7, Syn, CD56, CgA, CD34, CD117, EGFR, and Ki-67." (PMID 32149149, 2020). "These markers include clinical parameters such as the tumor size, FIGO stage, parametrial and lymph node invasion and the availability of BT but also molecular markers such as the expression of the epidermal growth factor receptor." (PMID 32429458, 2020). "The relationship between EGFR/EGFR-AS1 levels and tumor aggressiveness was evaluated by using the online available data of the TCGA." (PMID 31938054, 2020). "The genetic status of CDK4, EGFR and PDGFRA loci, under the influence of the tumor niche, drives the different states in a plastic way." (PMID 32570988, 2020). "FBLN3 is also shown to directly bind EGFR and affects its activation in NSCLC, though its effect on EGFR mediated tumor progression is marginal." (PMID 32719793, 2020). "Several studies found that the epidermal growth factor receptor (EGFR) family, particularly ERBB2 (a member of this family), was involved in alcohol-mediated tumor promotion." (PMID 33203443, 2020). "Near-infrared fluorescent dyes have been coupled to monoclonal antibodies cetuximab and bevacizumab, directed against EGFR and VEGF, respectively, in order to detect tumor tissue." (PMID 32942549, 2020). "L peptide is screened from the phage display peptide library with good epidermal growth factor receptor (EGFR) binding and tumor targeting characteristics." (PMID 32796618, 2020). "Deletion of EGFR in a mouse model of autochthonous lung cancer driven by KRASG12D reduced KRAS activity and transiently retarded tumor growth." (PMID 32560574, 2020). "GEM implantation reduced the protein level of EGFR by promoting its c-CBL-mediated ubiquitination and degradation, thus inhibiting its downstream effects, such as tumor cell growth, angiogenesis, and metastasis." (PMID 32111094, 2020). "AREG and EREG are required for autocrine EGFR signaling, indicating that EREG plays an important role in tumor progression." (PMID 32596278, 2020). "Among the 784 patients, univariate analysis showed that the tumour location, surgery type, vascular invasion, T and N stage, the levels of CEA and CA19–9, EGFR expression and neoadjuvant chemotherapy were significantly associated with OS." (PMID 32680468, 2020). "First, radiations given during radiotherapy imitate ligand–receptor interaction by inducing EGFR autophosphorylation, which stimulates PI3 kinase and Ras pathways thereby supporting growth and survival of tumor cells, and eventually leading to therapy failure." (PMID 35047986, 2020). "The group also developed 4-1BB-agonistic trimerbodies targeting EGFR and CEA, with minimal off-tumor cytotoxicity in vitro and in vivo." (PMID 32793488, 2020). "The researchers designed an EGFR-targeting fusion protein consisting of recombinant gelonin (rGel) toxin and EGF, and PCI of rGel-EGF was applied to EGFR expressing tumor cells in vitro and in vivo." (PMID 31936595, 2020). "Our findings first showed the roles of exosomes in EGFR‐TKI resistance transmission and provided novel insights into further understanding the contribution of tumour cell plasticity to drug resistance transfer." (PMID 31894895, 2020).
tumor (continued). "Targeted toxins consisting of the anti-EGFR scFv2112 from cetuximab or scFv1711 from panitumumab and the truncated version of Pseudomonas Exotoxin A (ETA’) were also tested against different tumor entities, including PCa." (PMID 33260619, 2020). "Then, we established five patient-derived tumor xenograft (PDX) models of HCC (LI6280, LI1097, LI0050, LI0334, LI6611) which have different expression of EGFR." (PMID 32079107, 2020). "Thus, a tumor of squamous origin with biomarkers/profile indicating dependence on EGFR signaling might be prevented from metastasizing by combining therapies that target EGFR signaling and iCa2+ signaling, while the combination might be counterproductive in another context." (PMID 32575848, 2020). "We examined the antitumor activities and potential resistance mechanism of a novel EGFR third-generation inhibitor in vitro and in vivo using ELISA, SRB assay, immunoblotting, flow cytometric analysis, kinase array, qRT-PCR and tumor xenograft models." (PMID 32404161, 2020). "Neutrophil elastase secreted from tumor-infiltrating neutrophils stimulated PAR2 and induced EGFR transactivation." (PMID 32121107, 2020). "The GEP and CNA pattern for the EGFR, CDK4, MDM4, and PDGFRA genes was available in 83/83, 68/83, 68/83, and 68/83 GBM tumor samples evaluated, respectively." (PMID 31963499, 2020). "It was found to reduce EGFR and VEGFR-2 phosphorylation, MVD and MMP-9 and MMP-2 expression and enhance tumor cell and EC apoptosis." (PMID 33302367, 2020). "Since NIR-PIT is applicable to any antibody that targets tumor cell surface antigens, NIR-PIT using an anti-mouse EGFR antibody, the target molecule in NIR-PIT clinical trials, would have been preferable." (PMID 32927646, 2020). "In this regard, we used the validated anti-EGFR CL4 nuclease-resistant RNA-aptamer, generated in our laboratory, which was previously found to inhibit the derived tumor growth of NSCLC, glioblastoma, and triple-negative breast cancer (TNBC)." (PMID 32024070, 2020). "Among the potential drug targets, we identified some well-known targets, including EGFR, ERBB2, and PARP1 as well as CDK2 and CDK4/6, which are related to the regulation of tumor cells development." (PMID 33287876, 2020). "EGFR and KRAS genes were classified as oncogenes and STK11, RB1 and MGA genes were classified as tumor suppressors." (PMID 32998690, 2020). "The expression of EGFR correlates with prognosis in patients with clear cell RCC, and suppression of the EGFR signaling pathway can retard the tumor progression." (PMID 32631368, 2020). "Because no standard treatment remained for this patient, we selected treatment with an EGFR-TKI, erlotinib, at 150 mg orally once a day, based on molecular profiling of the tumor." (PMID 33267781, 2020). "Here, we found that in subtype-1 tumours various phosphoproteins that participant in mTOR signalling – such as MTOR-pS2448, GSKB-pS21-S9, PDK-pS241 and growth factor receptors EGFR-pY1068 and ERBB-pY1248 – all exhibited increased phosphorylation 32,33." (PMID 31988390, 2020). "MSCs have been also shown to improve tumor progression, after injection to the tumor site, through secretion of several growth factors such as TGF-β, epidermal growth factor receptor, periostin, ANG1, PDGF, insulinlike growth factor, and IL-6." (PMID 32793565, 2020). "In this paper, we present information from image-localized biopsies that provides insight into the distribution and co-occurrence of EGFR and PDGFRA amplified sub-populations throughout GBM tumours in a cohort of patients." (PMID 33120534, 2020). "In the case of LMP1, different cargos have been found to be packaged into EVs, including EGF receptor (EGFR), fibroblast growth factor 2 (FGF-2), PI3K, and HIF1α, which play major roles in angiogenesis, tumor growth, and metastasis." (PMID 32546618, 2020). "ADAM17 was also shown to be overexpressed in gastrointestinal stroma tumours (GIST) where it co-localised with EGF and EGFR." (PMID 32698506, 2020).
tumor (continued). "In each case, 2 patients (4.8%) harbored CNV in all 3 exons of EGFR and FGFR1, and only one patient (2.4%) had CNV in both exons of TOP2A, suggesting that the whole genes were possibly amplified in the primary tumor." (PMID 33298978, 2020). "miR-7 is critical in the reversion of EMT due to AKT and ERK1/2 pathways inactivation, by reducing the epidermal growth factor receptor (EGFR) expression and thus inhibiting tumor metastasis." (PMID 31936634, 2020). "To evaluate DNA methylation and gene expression differences between “EGFR Wild Type/Low PD-L1 expression” NSCLC samples and non-tumor samples, we constructed 249-DMEGs and 297-DMSs-based random forest classifiers, followed by PCA and ROC analyses." (PMID 32899191, 2020). "Before, interactions with IGF1R, EGFR and MET receptors had been shown for flRON and several studies had demonstrated MSP-mediated tumor proliferation and progression involving the PI3K/AKT signaling pathway." (PMID 32272784, 2020). "STAT3 is a key factor downstream of EGFR signalling, and EGFR-mediated STAT3 activation is essential for skin carcinogenesis in mice." (PMID 32899142, 2020). "The expression levels of EGFR were found to correlate with adrenocorticotroph hormone (ACTH) and cortisol levels as well as tumor recurrence." (PMID 32012988, 2020). "PTPRK dephosphorylates and inactivates oncogenic proteins such as STAT3, EGFR and CD133, is frequently downregulated in human cancers, and is considered a tumor suppressor." (PMID 31934854, 2020). "Epidermal growth factor receptor (EGFR) is frequently overexpressed or activated in LAC, and promotes tumor initiation and progression in the early stages of cancer development." (PMID 32957649, 2020). "Immunohistochemical analysis revealed the changes of the expression levels of EGFR, AKT, and ERK 1/2 in the samples with different treatment from the tumor-bearing mice." (PMID 32850421, 2020). "CRM197 treatment inhibited tumor growth; and Western blotting showed CRM197 inhibited the expression of p-EGFR, p-ERK, HIF-1α, and VEGF in vivo, consistent with our in vitro results." (PMID 32695675, 2020). "EGFR and VEGF expression were high in primary tumor (median TIS 8) and LN metastases (median TIS 6 and 8, respectively)." (PMID 32942549, 2020). "Epidermal growth factor receptor (EGFR or ErbB1), a tyrosine kinase receptor, is a key factor in epithelial malignancies, in terms of enhancing tumor growth, invasion, and metastasis." (PMID 32521802, 2020). "Based on the results of the univariate analysis tumour stage, tumour size, host response, differentiation, POI, and EGFR expression were fitted to the statistical model." (PMID 33123565, 2020). "In these cells, the intra-tumor levels of human/mouse EGF and EGFR varied according to the treatment." (PMID 31938054, 2020). "The 89Zr-labeled EGFR-specific affibody, ZEGFR:03115, showed tumor uptake as early as 3 h after injection." (PMID 32560337, 2020). "Recently, one study demonstrated both circulating tumor cells exhibiting an active EMT status (vimentin+ and EGFR+) and tumoral expression of AXL mRNA as prognostic factors for OS and RFS of patients with early stage resectable NSCLC." (PMID 32674274, 2020). "Multivariate cox regression demonstrated that EGFR, HER4, EphA3 or the panel of high expression of these proteins was an independent prognostic factor for tumor recurrence." (PMID 32093644, 2020). "The schema points out that gefitinib-untargetable palmitoylated EGFR impinges on FASN, promoting tumor growth via the AKT pathway." (PMID 32516941, 2020).